PIEZO1 (piezo type mechanosensitive ion channel component 1 (Er blood group))
Diseases named in the same sentence as PIEZO1 in open-access papers (continued):
Sharing a sentence is not in itself a finding about the gene and the disease.
cancer (continued). "In conclusion, overcoming challenges of specificity and off-target effects in Piezo1-targeted therapies could represent a major breakthrough in cancer treatment." (PMID 41437911, 2026). "Targeting key nodes that regulate network balance may yield more specific and effective anti-cancer strategies than approaches focused solely on inhibiting Piezo1." (PMID 41437911, 2026). "Therefore, targeting Piezo1 to modulate ECM stiffness is a potential therapeutic target in cancer treatment." (PMID 41437911, 2026). "While Piezo1 facilitates the anti-cancer effects of ES, SUN1 acts as a negative regulator." (PMID 39940798, 2025). "Genomic alterations in PIEZO1 were found in 4% of pan-cancer patients." (PMID 40977743, 2025). "Further investigation using the HPA dataset revealed PIEZO1 mRNA in multiple cancer cell lines." (PMID 40977743, 2025). "Pronounced bending of the bilayer can perturb the state of Piezo1 channels, resulting in an uncontrollable increase in calcium influx that may perturb intracellular calcium homeostasis in cancer cells." (PMID 40727658, 2025). "In addition to these, PIEZO1 markedly affects cancer development, progression, and invasion, with increasing studies suggesting that its abnormal expression correlates with invasiveness and metastasis of cancer cells." (PMID 40977743, 2025). "As such, elevated PIEZO1 expression may emerge as a promising prognostic biomarker in cancer management." (PMID 40977743, 2025). "Our analysis revealed that PIEZO1 promotes oncogenic processes across various cancers." (PMID 40977743, 2025). "Based on these observations, we next sought to functionally assess whether PIEZO1 activation is directly involved in regulating the cancer stem cell-like phenotype." (PMID 40890143, 2025). "Our study and other previous studies have shown that Piezo1 is critically involved in regulating various types of immune cell functions, including those of dendritic cells (DCs), neutrophils and T cells, in inflammation and cancer." (PMID 39890818, 2025). "Piezo1, integrins, and YAP are also strongly associated with cancer immunity." (PMID 40061015, 2025). "An important next step will be to examine whether similar mechanisms operate in patient-derived cancer cells and tissues by assessing PIEZO1 expression and its potential correlation with stemness markers and epigenetic changes." (PMID 40890143, 2025). "This study used The Cancer Genome Atlas (TCGA) data to analyze PIEZO1 expression profiles." (PMID 40977743, 2025). "PIEZO1 plays a complex and multifaceted role in cancer development and progression." (PMID 40724850, 2025). "The results demonstrated that high PIEZO1 expression remained an independent risk factor for poor prognosis across multiple cancers, significantly shortening OS, DSS, and PFI in patients with various cancer types (HR > 1, p < 0.05);." (PMID 40977743, 2025). "The specific Piezo1 inhibitor GsMTx4 has demonstrated preliminary efficacy in preclinical studies, where it suppresses the self‐renewal capacity of cancer stem cells and induces apoptosis by blocking Piezo1‐mediated calcium signaling, ultimately prolonging survival in murine models." (PMID 40667648, 2025). "This suggests that interventions targeting Piezo1 in cancer therapy may simultaneously impact both the TME and the surrounding normal tissues." (PMID 41195420, 2025). "Eventually, the Piezo1/integrin β1 signaling axis promoted cellular uptake and transport of peptides, establishing a positive feedback loop, promoting mechanical delivery to cancer and offering possibilities for drug modification in cancer therapy." (PMID 39258781, 2024). "For instance, identifying signals activated only in wound environments, such as Piezo1-induced EGFR signaling may provide better targets for cancer." (PMID 39636982, 2024).
cancer (continued). "PIEZO1 expression has also been demonstrated to contribute to various physiological processes within the hallmarks of cancer, including epithelial–mesenchymal transition (EMT), angiogenesis, hypoxia, metabolic alteration, inflammation, and the functional gain or loss of various signaling pathways." (PMID 38398074, 2024). "In summary, PIEZO1 acts as a cancer suppressor by regulating the ROS/Wnt/β‐catenin axis, providing a new perspective on the role of mechanosensitive channel proteins in cancer." (PMID 38494915, 2024). "A growing body of research suggests that Piezo1 has a potentially important role in cancer therapy." (PMID 38690080, 2024). "PIEZO1 works differently in different cancers and at different stages of development." (PMID 38494915, 2024). "While Piezo1 is expressed in different cell types, such as endothelial cells; cardiomyocytes; blood cells; cancer cells; stem cells; and progenitors such as hematopoietic stem cells, osteoblasts, adipocytes and astrocytes, its distribution in the cells is dynamic and varies from cell to cell." (PMID 38534326, 2024). "YAP, as a classic marker that is also highly expressed in many malignant tumors, has been found to play a synergistic role with Piezo1 in the progression of many diseases and tumors, but the upstream and downstream relationship and activation mode of the two remain to be determined." (PMID 38690080, 2024). "Piezo1 has been found to be involved in many different physiological and pathological processes where cell migration is fundamental, such as skin wound healing, cancer metastasis, immune response of brain microglia, and cell spreading on micro-patterns." (PMID 38581527, 2024). "Future studies could further evaluate the intersection of PIEZO1 and junctional proteins in the context of cancer progression pathways." (PMID 38632473, 2024). "Also, new studies on the effect of Piezo1 on the stemness of various stem cells are emerging, but few studies extend it to cancer stem cells." (PMID 38690080, 2024). "In the Hong Kong cohort, NFKB1/RELA and PIEZO1 expression in identical samples were assessed through IHC, and their protein levels showcased a direct correlation when scoring the positive cancer cell percentage (n = 128)." (PMID 37983931, 2023). "To reinforce the role of PIEZO1 in fibroblast‐driven cancer progression, we applied a fibroblast proliferation gene set to analyze Yoda1‐treated RNA‐seq data through GSEA, uncovering a positive association between PIEZO1 activation and fibroblast proliferation." (PMID 37983931, 2023). "Thus, Piezo1 seems to be mostly protumoral, acting through diverse mechanisms and playing a key role in certain hallmarks of cancer: migration, invasion and angiogenesis." (PMID 37762011, 2023). "Force-induced calcium influx via Piezo1 can be exploited to target cancer cells." (PMID 37864030, 2023). "Our results suggest that mechanical activation via Piezo1, Src, and p38 may be more relevant to controlling repair, regeneration, and cancer growth than tyrosine kinase signaling via canonical EGF signaling, suggesting an alternative therapeutic approach." (PMID 37756411, 2023). "However, it was found that Piezo1 is also expressed in normal breast cells, but a higher expression characterizes cancer cells." (PMID 36837670, 2023). "Piezo1 is a mechanosensitive cationic channel protein involved in cancer progression." (PMID 37306789, 2023). "In our IHC‐stained sections, we observed that PIEZO1 was primarily expressed in cancer cells." (PMID 37983931, 2023). "Piezo1 expression and function are altered in multiple cancers." (PMID 37306789, 2023). "However, the interplay between α‐SMA+ CAFs and PIEZO1 within cancer cells, including its activation mechanism, subsequent signaling pathways, and role in GC microenvironmental alteration, remains to be uncovered." (PMID 37983931, 2023). "Piezo1 disturbs these processes leading to greater cancer cell motility." (PMID 36837670, 2023).
cancer (continued). "Recent studies also indicate that Piezo1 plays a key role in cancer evolution." (PMID 37781915, 2023). "Moreover, it has been demonstrated that Piezo1 signaling in inflammatory cells promotes cancer progression and myeloid-derived suppressor cell expansion." (PMID 36837670, 2023). "Given PIEZO1's role as a calcium channel protein, we assessed calcium influx in cancer cells." (PMID 37983931, 2023). "In the case of Piezo1 knockdown, cancer cells present an enhanced sensitivity to Cisplatin or 5-FU." (PMID 36837670, 2023). "Piezo1 activation increases the mitochondrial membrane potential, which is responsible for many basic cell processes, including cell proliferation, but also gene transcription, differentiation, cell death, cancer metastasis, and angiogenesis." (PMID 36837670, 2023). "Various studies have shown that due to the influence of Piezo1 on the EMT process, this mechanosensitive channel could be considered one of the causes of cancer dissemination." (PMID 36837670, 2023). "Piezo1 downregulation reduces migration and invasion of cancer cells." (PMID 36837670, 2023). "This review summarizes the recent progress made in understanding the immunoregulatory role and mechanisms of the mechanical receptor Piezo1 in inflammation and cancer and provides new insight into the biological significance of Piezo1 in regulating immunity and tumors." (PMID 36615408, 2022). "The elimination of Piezo1 in myeloid cells could prevent the development of cancer and enhance survival rates for multimicrobiological sepsis." (PMID 36615408, 2022). "On the contrary, more reports reminded that Piezo1 might function as an oncogene-related molecule in several types of cancer." (PMID 35461277, 2022). "We first assessed the PIEZO1 expression levels in different cancers." (PMID 35747124, 2022). "In almost all cancers, we found that PIEZO1 expression was remarkably related to immune-related pathways, such as innate immune response, adaptive immune response, inflammatory response and some inflammatory cells, such as neutrophils, lymphocyte and leukocyte." (PMID 35747124, 2022). "Whether PIEZO1 can affect the pathogenesis of variety types of cancer by some certain molecular pathways remains to be explored." (PMID 35747124, 2022). "During the past years, Piezo1 has been widely studied in cancers." (PMID 35991548, 2022). "PIEZO1 alteration is among the most common genetic alterations in human cancers." (PMID 35747124, 2022). "We found that Piezo1-induced calcium flux upregulated membrane ruffling and cancer cell survival." (PMID 35646889, 2022). "Thus, our findings provide new insights into the function of Piezo1, suggesting that Piezo1 plays a significant role in the behavior of cancer cells." (PMID 35646889, 2022). "Dendritic cell (DC)-specific Piezo1 regulates T cell differentiation in cancer." (PMID 35993548, 2022). "Furthermore, we demonstrate that Piezo1-mediated Ca2+ influx upregulates membrane ruffling, a characteristic feature of cancer cell metastasis, using spatiotemporal image correlation spectroscopy." (PMID 35646889, 2022). "We believe that through the utilization of these technologies Piezo1 could be studied further leading to insight into various CVDs and other diseases like cancer." (PMID 35173527, 2022). "Additionally, myeloid cells Piezo1 depletion promoted endurance in polymicrobial sepsis and guard from cancer." (PMID 35173527, 2022). "In contrast, one study indicates that an increase in mechanical stiffness may promote the activation of dendritic cells during cancer immunotherapy by activating the mechano-signal transducers Piezo1 and TAZ." (PMID 35331296, 2022). "This suggests that mechanical stimuli may lead to opposing cellular behaviors and our data is important to clarify the pro-cancer role of Piezo1 in OC development." (PMID 35942515, 2022).
cancer (continued). "Hence, we analyzed calcium flux through Fluo-8 calcium indicator in A1847 cells treated with 50 μM of Yoda1, and we found that Yoda1 increased intracellular calcium levels, which is crucial for the Piezo1-mediated cancer metastasis." (PMID 35942515, 2022). "This suggests that inhibition or activation of Piezo1 could be a potential target for the treatment of cancer." (PMID 36615408, 2022). "In this study, we hypothesized that Piezo1 channels mediate the compression-enhanced invasive phenotype of cancer cells." (PMID 34979904, 2022). "In this review paper, we will discuss the various roles of Piezo1 in cancer metastasis and how Piezo1 could be leveraged in future cancer therapies." (PMID 34831037, 2021). "Piezo1 encompasses the broad range of effects that mechanical forces can have on cancer progression and indicates the clear need for further research into the effects of mechanotransduction in cancer metastasis." (PMID 34831037, 2021). "Interestingly, Piezo1 also links physical forces to immune regulation in myeloid cells, and these cells regulate cancer and infectious disease." (PMID 33422128, 2021). "Piezo1 has also been found to play a role in shear stress-induced release of ATP in red blood cells (RBCs), where paracrine signaling prompts the formation of inter-endothelial junctions and supports intravasation and extravasation of cancer cells." (PMID 34831037, 2021). "The growing interest in Piezo1 in immune cells may provide insight into how it functions in cancer cells and how modulating Piezo1 activity may lead to potential cancer immunotherapies and treatment of infectious disease." (PMID 34831037, 2021). "In a study with cholangiocarcinoma cells, Piezo1 knockout inhibited EMT in cancer cells." (PMID 34831037, 2021). "Piezo1 also exhibits therapeutic potential for aging and cancer immunotherapy." (PMID 33649312, 2021). "In particular, they identified mechanosensitive ion channels called Piezo1 as key players in WSS-induced TRAIL-mediated apoptosis of cancer cells (COLO 205 and MDA-MB-231 cell lines), decoding one of the possible WSS-induced mechanism impairing CTCs survival in the bloodstream." (PMID 33444361, 2021). "Likewise, in SCLC the depletion of Piezo1 using siRNA resulted in increased cell migration and induced anchorage-independence growth in cancer cells, thus confirming the oncosuppressive role of Piezo channels in lung malignancies." (PMID 32635333, 2020). "Because PIEZO1 is also known as Fam38A, an integrin-interacting protein, we hypothesized that its dysfunction may affect cancer cell survival." (PMID 29757938, 2018). "Additionally, Piezo1-mediated calcium influx induced by circulatory shear stress increases susceptibility of cancer cells towards TRAIL-induced apoptosis 157, underscoring the potential of targeting Piezo1/2 in cancer therapy." (PMID 40083943, 2025). "Additionally, targeting specific mechanosensitive ion channels, such as TRPM7, Piezo1, or PANX1, may provide new therapeutic strategies for diseases associated with calcium signaling, such as cancer, heart diseases, and inflammation." (PMID 40507332, 2025). "Hence, PIEZO1 may contribute to cancer progression by regulating the ECM-receptor signaling pathway." (PMID 40977743, 2025). "In addition, long-term survivors also have antibodies against proteins known to promote cancer growth, such as PIEZO1, aggressiveness such as TMPRSS2, and Epithelial Mesenchymal Transition such as KIAA1217 or C11orf45, which are biomarkers related to immune checkpoint proteins." (PMID 40887652, 2025). "Moreover, the prognostic implications of Piezo1 expression and activation are cancer‐specific." (PMID 40583158, 2025). "However, other studies employing different lines have produced similar results, indicating an association between PIEZO1 and poor prognosis, probably through the induction of a compression-enhanced invasive phenotype and matrix degradation of cancer cells through Piezo1 channels." (PMID 39001475, 2024).
cancer (continued). "Interestingly, Piezo1 seems to be a link between metabolism and DC function, as the channel was shown to activate a DC-driven differentiation of TH1 and T regulatory (Treg) cells in cancer in association with changes in glycolysis pathways." (PMID 38534326, 2024). "However, there are many other cancer types in which Piezo1 is usually upregulated." (PMID 37762011, 2023). "The observation that genetic deletion of Piezo1 in myeloid cells protected against cancer suggests that Piezo1 could be a target for suppressing inflammation in different organs, including GI tract cancers, although the potential for immunosuppressive side effects of such a strategy is unknown." (PMID 37781915, 2023). "Modification of the PIEZO1 gene could be a promising method to cure cancers." (PMID 35747124, 2022). "Furthermore, given that carcinogenesis is associated with significant changes in mechanical properties of the affected cells and tissues that contribute to the malignancy of the respective types of cancers, the expression of both Piezo1 and Piezo2 varies largely in different types of cancers." (PMID 35340591, 2022). "However, it is still unclear whether Piezo1-targeted DCs affect the differentiation of different subsets of T cells in cancer." (PMID 35993548, 2022). "Information about Piezo channels’ regulation by low oxygen pressures is absent in cancer and the literature data are limited to a few works in red blood cells and pulmonary endothelial and smooth muscle cells, where the pathogenic role of Piezo1 was explored." (PMID 35806388, 2022). "A recent study revealed that the force-dependent co-localization of Piezo1 to β3 integrin could be synergistic with downstream events and provides a mechanism of tension-dependent vascular growth that is critical in the development process and cancer." (PMID 36457052, 2022). "Global inhibition of Piezo1 using peptide inhibitors reduces MDSC numbers, which can positively impact cancer progression." (PMID 41437911, 2026). "This research has shown that physiological fluid shear stress activates mechanosensitive ion channels (MSCs), such as Piezo1, enhancing TRAIL‐mediated apoptosis in cancer cells." (PMID 39976192, 2025). "Here we report that pathological activation of PIEZO1 differentiated human PSCs into an inflammatory CAF phenotype that expresses chemoresistance and cancer stemness markers CD10 and GPR77." (PMID 41100488, 2025). "We investigated the correlation between PIEZO1 expression and OS, DSS, as well as PFI among patients with various cancers using Cox regression analysis and Kaplan-Meier analysis." (PMID 40977743, 2025). "In prostate cancer cells, compression of the cell membrane by a glass probe activates Piezo1, which enhances ICW and subsequently activates the Akt/mTOR signaling cascade, promoting cancer cell proliferation, migration, and cell cycle progression." (PMID 40507332, 2025). "The inactive ion channel Piezo1 can act on downstream effectors through the Hippo/YAP axis, thereby preventing cancer cell metastasis, inducing cell death, and inhibiting proliferation." (PMID 41017814, 2025). "In pancreatic ductal adenocarcinoma (PDA) mouse models, Piezo1 deletion from myeloid cells was found to result in enhanced intratumoral CD4+ and CD8+ T-cell activation and protection against cancer progression." (PMID 38534326, 2024). "Therefore, targeting Piezo1/integrin β1/YAP axis may be a promising strategy for cancer treatment." (PMID 39258781, 2024). "In the context of cancer pathophysiology, alteration in the function and expression of TRP channels and Piezo1 in cancer has been reported, impacting various cellular processes in tumors, such as differentiation, migration, and invasion." (PMID 38193763, 2024). "Piezo1-mediated Ca2+ influx can activate NFAT signaling, which is known to promote cancer stem cell populations and stemness features." (PMID 37306789, 2023).